SCGB1D4 (secretoglobin family 1D member 4)
Description:
Seems to be involved in the regulation of chemotactic cell migration and invasion.
Synonyms: IIS
Tractability: Antibody: UniProt places it where antibodies can reach, with medium confidence; UniProt predicts a signal peptide or a membrane-spanning region; its Gene Ontology location is reachable by antibodies, with medium confidence.
Gene: Protein-coding gene on chromosome 11 (62,296,281 to 62,299,075, reverse strand). Ensembl gene ENSG00000197745.
Subcellular location: Secreted
Gene Ontology:
Cellular component: extracellular region
Genetic constraint (gnomAD): Loss-of-function variants: 5 observed, 7.56 expected, observed/expected ratio (o/e) 0.66, 90% interval 0.34 to 1.38. That is too few expected variants to judge how well the gene tolerates losing a copy. Missense variants: 91 observed, 97.16 expected, observed/expected ratio (o/e) 0.94, 90% interval 0.79 to 1.12. Synonymous variants: 34 observed, 38.84 expected, observed/expected ratio (o/e) 0.88, 90% interval 0.67 to 1.16.
Homologues: Orthologues: chimpanzee SCGB1D4 (100% identical), macaque SCGB1D4 (55% identical), rabbit SCGB1D1 (52% identical), rabbit SCGB1D (48% identical), pig SCGB1D1 (45% identical), rat Scgb1d2 (40% identical), rat Scgb1d4 (36% identical), rat AABR07006242.1 (35% identical). Paralogues in human: SCGB1D2 (55% identical), SCGB1D1 (52% identical).
Diseases named in the same sentence as SCGB1D4 in open-access papers:
SCGB1D4 is named in the same sentence as 2 diseases in open-access papers, as found by Europe PMC text mining. Sharing a sentence is not in itself a finding about the gene and the disease.
SCGB1D4 shares sentences with these, for which no sentence is quoted: adenoid hypertrophy (1 paper); ovarian carcinoma (1).